IFNG (interferon gamma)
Diseases named in the same sentence as IFNG in open-access papers (continued):
Sharing a sentence is not in itself a finding about the gene and the disease.
asthma (continued). "Flow cytometry analyses found CD3 + CD4 + IFNγ + T lymphocytes amongst cells collected from BAL, suggesting that Th1 inflammation promotes corticosteroid insensitivity in severe pediatric asthma." (PMID 35578269, 2022). "To further understand the effects of TNFα and IFNγ on corticosteroid sensitivity in the context of neonatal and pediatric asthma, we performed RNA sequencing (RNA-seq) on human pediatric ASM treated with fluticasone propionate (FP), TNFα, and/or IFNγ." (PMID 35578269, 2022). "This is because it can decrease oxidative stress, serum levels of immunoglobulin E (IgE), IL4, transforming growth factor (TGF-β), and increase interferon-gamma (IFN-γ) and IL-10 in the OVA-induced asthma model." (PMID 33959015, 2021). "For example, iNKT cell-derived IFNγ showed a protective effect against Th2-related diseases such as asthma, whereas iNKT cell-derived IL4 increased the pathogenicity of asthma." (PMID 34829848, 2021). "Asthma‐2 (n = 19) combined a pro‐inflammatory signature, with a Th2 and innate immune response with upstream modulators of IL‐1β, TNF, IL‐13, IL‐15, and IFNγ." (PMID 34962717, 2021). "Emphasizing the complexity of asthma, markers of TH1 responses, such as TNFα and IFNγ were also elevated in mice of both genotypes." (PMID 29728628, 2018). "Th1-related cytokines include interferon gamma (IFN-γ), which affects the severity of asthma, and interleukin 12 (IL-12), which induces Th1 cells and suppresses Th2 cells." (PMID 29151835, 2017). "Moreover, sterile fecal waters from such at-risk infants induced a higher proportion of IL-4-secreting compared to IFNγ-secreting adult CD4+ cells, linking fecal metabolites to possible immune cell alterations that could play a role in increased asthma risk for these children." (PMID 28596951, 2017). "CpG promoter loci of asthma genes (i.e., interleukin 4 (IL4), interferon gamma (IFNγ), inducible nitric oxide synthase (NOS2A), arginase 2 (ARG2)) were pyrosequenced and lung function was assessed." (PMID 28424066, 2017). "The effect of dexamethasone varied between cytokines, with IL-17 being inhibited less than IL-13 and IFNγ (ANOVA analysis in healthy subjects and asthma; p = 0.0002 and p = 0.0006 respectively)." (PMID 27716212, 2016). "Administration of L. johnsonii (La-1) to mice with branchial induced asthma dampened the autoimmune response by reducing the proportion of CD4+ T lymphocytes expressing IL-4 and increasing CD4+ T lymphocytes expressing IFNγ." (PMID 26275147, 2015). "In this study, the IFNγ level in rAdV-CTLA4Ig and rAdV-CCR7-modified DC-treated mice was significantly lower than that of asthma, control or rAdV-GFP treated mouse." (PMID 25177863, 2014). "As DNA methylation in different tissue types can vary and appropriate biomarkers for epigenetic asthma research are needed, we sought to determine the relationship between CD4+ lymphocyte and buccal cell IFNγ promoter methylation in allergic asthmatics." (PMID 24891923, 2014). "In mild asthma, Il10 showed the largest change in expression followed by II5, II4, Tnfα, Il6, Il2, Il13, and Ifnγ, respectively." (PMID 23781124, 2013). "We also assessed Teff from the six MZT pairs discordant for both asthma and SHS exposure for levels of IFNγ." (PMID 23226205, 2012). "Additionally, the downregulation of IFNG and FOXP3 in asthma patients indicates suppression of regulatory immune responses." (PMID 40309741, 2025). "Furthermore, this study utilized network pharmacology to identify pivotal asthma treatment targets for YKS, including AKT1, TNF, IL1B, EGFR, IFNG, IL4, CASP3, and PTGS2." (PMID 40420184, 2025). "Severe asthma patients often do not have high type 2 inflammation but rather exhibit a mixed inflammatory response with increases in IFNγ and other type 1 inflammatory features." (PMID 40297693, 2025).
asthma (continued). "Interferon-gamma (IFN-γ): It plays a multifaceted and contradictory role in the pathophysiology of asthma, particularly affecting the differentiation between type 2-high (T2-high) and type 2-low (T2-low) asthma phenotypes." (PMID 40564060, 2025). "Importantly, IDO expression is regulated by interferon-gamma (IFN-γ), a cytokine critical in antiviral and antibacterial defense which can further dampen inflammatory responses in asthma by modulating Th1/Th2 balance." (PMID 39882630, 2025). "In vivo studies using animal models of severe asthma have suggested that IFNγ, but not IL-17, is responsible for heightened AHR48." (PMID 38081868, 2023). "Administration of IL-6 inhibitor in mice with HDM-induced asthma did not result in reduced frequency of Th1-cells and IFNγ secretion and also the frequency and number of Th2-cells in the airways as compared to the saline control group." (PMID 35408882, 2022). "Moreover, high numbers of IFNγ-producing CD8+ T-cells were increased and correlated with asthma severity." (PMID 36012240, 2022). "Collectively, our studies show that combined exposure to TNFα and IFNγ impairs corticosteroid sensitivity in ASM and may contribute to persistent symptoms and exacerbations in severe pediatric asthma." (PMID 35578269, 2022). "Furthermore, the inability of corticosteroids to reduce TNFα/IFNγ-induced VCAM1 and antigen presenting genes implicate ASM-T cell interactions in persistent airway inflammation and thickening in severe asthma." (PMID 35578269, 2022). "It is thus not surprising that IFNγ is found to be increased in sputum and blood-derived cells from patients with SA compared to those with mild-to-moderate asthma." (PMID 35387021, 2021). "Like Asthma‐3, they had high AQLQ score and low levels of ISG15/IFNγ and C3." (PMID 34962717, 2021). "In our initial report, we demonstrated that doxycycline suppresses C. pneumoniae mediated interferon-gamma responses in PBMC from children with asthma; azithromycin did not decrease IL-4 or IgE responses." (PMID 32511255, 2020). "While much research has focused on IFNγ as a pro-inflammatory mediator of severe asthma, altering airflow obstruction and steroid responsiveness, type I and III IFNs have also been shown to be up-regulated in asthma." (PMID 33101299, 2020). "The levels of these PAHs were correlated with asthma-related biomarkers including immunoglobulin E (IgE), resistin, granulocyte–macrophage colony-stimulating factor (GMCSF) and interferon gamma (IFN-γ) as well as the cytokines; interleukin (IL)-4, IL-5, IL-8 (CXCL8) and IL-10." (PMID 33187512, 2020). "Studies have shown IFNγ+ CD4+ T cells are more prevalent in the airways in severe asthma versus mild, moderate disease and that IFNγ-induced expression of CXCL10 and down-regulation of SLPI lead to increased AHR and steroid resistance in severe asthma." (PMID 33101299, 2020). "Cells of the immortalized murine macrophage cell line RAW264.7 were treated with cytokines that are known to act in the pathology of asthma (CytoMix), i.e. IFNγ, IL-1β, and TNFα in the presence or absence of recombinant Grx2 WT or Grx2 C40S." (PMID 33224135, 2020). "While the role of type II IFN (IFNγ) in asthma has been the subject of considerable investigation, new research shows that type I and III IFNs may also have a hand in asthma development and exacerbation." (PMID 33101299, 2020). "Additionally, Th1 cells, through production of interferon-gamma (IFN-γ), can suppress the Th2 effector functions in the development of asthma." (PMID 32411263, 2019). "In the current study, the inflammatory cytokines, IL17A, IL33, and IFNγ, were elevated in serum of patients with both allergic and nonallergic asthma, reflecting an active inflammatory state in all our asthmatic patients." (PMID 30306094, 2018). "Similar associations were not apparent between BC and DNA methylation of other asthma gene promoters (i.e., IFNγ, NOS2A, and ARG2) in unadjusted and adjusted models (p > 0.05)." (PMID 28588744, 2017).
asthma (continued). "Interestingly, the level of IFNγ, a Th1 cytokine, in the BALF of mouse treated with DCs modified by rAdV-CTLA4Ig alone was significantly higher than that of asthma mouse in our previous study." (PMID 25177863, 2014). "Here, we use primary AEC cultures stimulated with TNFα and interferon γ (IFNγ) to determine whether dysregulation of XIAP, cIAP1, and cIAP2 contributes to apoptosis observed in asthma-related inflammation." (PMID 24303189, 2013). "We hypothesized that maternal exposure to airborne PAH may induce altered methylation status of the asthma genes IL4 and IFNγ." (PMID 22562770, 2012). "The finding that systemic levels of IL-12 (p40), IL-5, and IFNγ/IL-5 reflect the regulatory differences between the allergic and non-allergic pediatric asthma subgroups, led us to address this issue more closely." (PMID 21179211, 2010). "The acute asthma model had elevated IFNγ relative to untreated mice which was not detectable (n = 4, p < 0.05), which is consistent with the literature." (PMID 20974000, 2010). "Notably, alterations in the ratios of interferon gamma (IFN‐γ) and interleukin 4 (IL‐4) signify a critical disturbance in the Th1/Th2 balance, which is essential in the progression of allergic syndromes such as asthma and allergic rhinitis." (PMID 41523289, 2026). "Th1 cells produce interferon-gamma (IFN-γ), a cytokine that enhances macrophage activation and promotes a pro-inflammatory response that is commonly observed in non-allergic, infection-driven, or pollutant-exacerbated asthma." (PMID 40508095, 2025). "Besides, currently no biologics targeting IFNγ for asthma have been developed, which leaves this door completely open for research." (PMID 40564060, 2025). "Furthermore, this immunosuppressive effect could be significantly enhanced by pre-treating the DFSCs with interferon-gamma (IFN-γ), indicating that the cells’ therapeutic activity efficacy can be a future cell-based treatment for allergic diseases like asthma." (PMID 41007215, 2025). "However, administration of nebulized recombinant IFNγ or subcutaneous human IL‐12 to asthma patients did not improve disease symptoms." (PMID 40016948, 2025). "Thus, in contrast to the Type 2 (T2 or eosinophilic) type of asthma which was mediated by IL-4, IL-5, and IL-13, the profile of the inflammatory mediators with high levels of IL-6, CXCL8, and IFNγ after TLR stimulation mirrored that of the non-T2 endotype of asthma." (PMID 39614276, 2024). "To identify the micro-environmental signals underlying Tc2 cell abundance in asthma, we exposed WT mice to inhaled HDM in the presence or absence of recombinant-IFNγ (recIFNγ), which skews the lungs microenvironment towards a mixed type-1/type-2 cytokine milieu." (PMID 37612281, 2023). "Recent studies have revealed that IFNγ could up-regulate and down-regulate the expression of CXCL10 and SLPI, respectively, which further resulted in increased AHR and steroid resistance in severe asthma." (PMID 35187081, 2022). "The undetectable levels of interferon gamma may be a reflection of the lack of an inflammatory process among our asthma cases and controls." (PMID 31336954, 2019). "However, recombinant subcutaneous administration of IFNγ had no benefit in the treatment of steroid-dependent asthma." (PMID 27814709, 2016). "Interestingly CXCL10 production induced by IFNγ or cytomix is also not inhibited by current asthma therapies such as fluticasone and/or salmeterol, whereas IL-1β- and TNF-α-induced release is markedly reduced by these agents." (PMID 24648846, 2014). "In this current study we sought to compare DNA methylation levels at highly conserved (between human and mouse) CpG sites in the IFNγ gene promoter region (CpG -186 and -54) between CD4+ T lymphocytes and buccal cells in a select cohort of allergic-sensitized children and adults with asthma." (PMID 24891923, 2014). "Cholesterol did not alter the IFNγ production in PBMCs from asthma patients and healthy controls." (PMID 23091602, 2012).
asthma (continued). "Although ASM are likely not a primary antigen presentation cell in asthma, their increased expression of adhesion molecules and antigen presentation gene in response to TNFα and IFNγ highlight that ASM-T cell interactions may be important and warrant further investigation." (PMID 35578269, 2022). "One possibility could be that, even though pro-inflammatory cytokines (IL-4, IL-13, IFNα, IFNγ, IL-17) upregulate many genes in epithelial cells (684–2,876 at 5% FDR in our analyses), they do not significantly interact with polygenic risk factors for asthma in epithelial cells." (PMID 39197446, 2024). "Asthma‐3 had high AQLQ score and lacked control of bacterial infection by low levels of ISG15, IFNγ, and C3." (PMID 34962717, 2021).
malaria (609 papers, 2005 to 2026). Malaria is a serious and sometimes fatal disease caused by a parasite that commonly infects a certain type of mosquito which feeds on humans. "A study aiming to analyze the relationship between the SNP rs2069705 (IFNG) and susceptibility to severe malaria in pregnant women categorized three groups: mild malaria, severe malaria, and the control group." (PMID 39066175, 2024). "Collectively, our data suggest that malaria-specific, IL-10 and IFNγ producing Tr1 cells are more commonly found in primigravid women and are associated with an increased risk of malaria in pregnancy." (PMID 37634385, 2023). "An imbalance of cytokines such as tumor necrosis factor (TNF), interleukin-6 (IL-6), IL-10, and interferon-gamma (IFN-γ) are implicated in malaria related-inflammation that induce changes in iron absorption and delocalization." (PMID 36183114, 2022). "Inflammatory CD4+ T-cells that produce IFNγ and TNFα have been implicated in conferring protection from malaria in adults by preventing P. falciparum infection or its replication such that higher parasitemia and clinical malaria are diminished." (PMID 34414129, 2021). "IFNG haplotypes and risk of iron deficiency, iron deficiency anaemia and anaemia at the end of the malaria season." (PMID 32420456, 2020). "IFNG genotypes and risk of iron deficiency, iron deficiency anaemia and anaemia at the end of the malaria season." (PMID 32420456, 2020). "Enhanced frequencies of IFNγ-secreting NK cells upon malaria vaccination were associated with antigen-specific IL-2 secretion and considered as a marker for antigen-specific T cell activation." (PMID 32517137, 2020). "Here, the authors show that malaria-associated pulmonary vascular damage is a consequence of IFNγ-activated lung endothelial cells capturing, processing, and cross-presenting malaria parasite antigen to specific CD8+ T cells induced during infection." (PMID 31534124, 2019). "Some P. falciparum-specific cytokine responses have been associated with protection against clinical malaria, including interferon gamma (IFN-γ), interleukin-10 (IL-10) and tumour necrosis factor (TNF)." (PMID 31806027, 2019). "In both mouse and human studies, IFNγ has been associated with control of parasitaemia, protection from malaria, and delayed reinfection." (PMID 31533835, 2019). "Of note, P2X7 deficiency led to better control of P. yoelii 17XNL malaria whose outcome seems to depend more on anti-parasite antibodies and less on IFNγ than in Pc malaria." (PMID 28859168, 2017). "Elevated IFNγ responses during blood-stage malaria have been associated with impaired humoral immune responses." (PMID 27812214, 2016). "A population of 267 individuals from Brazilian Amazon exposed to malaria was genotyped for five single nucleotide polymorphisms (SNPs), IFNG + 874 T/A, IL10A-1082G/A, IL10A-592A/C, IL10A-819 T/C and NOS2A-954G/C." (PMID 25627396, 2015). "Malaria mortality is associated with exaggerated host responses to inflammatory factors such as interferon gamma (IFNγ), tumor necrosis factor alpha (TNFα), free heme, C-X-C motif chemokine 10 (CXCL10) and parasite-derived cytotoxins." (PMID 26555697, 2015). "Few studies find associations between severe malaria and IFNG + 874 T/A polymorphism and these associations were weak and not significant after correction for multiple comparisons." (PMID 25627396, 2015). "This indicates that protection against blood-stage malaria is associated with low production of IL-1β, TNFα, IL-6 and a high biphasic production IFNγ by the liver." (PMID 25408684, 2014). "Our data show that sustainable protection against malaria associates with distinct intra-hepatic immune responses characterized by strong IFNγ producing CD8+ memory T cells." (PMID 22563506, 2012). "CPS clinical trials show that protection sustained for more than two years associates with malaria specific IFNγ responses that last for at least 14 months." (PMID 22563506, 2012).